CEP112 (centrosomal protein 112)
Description:
Recruits mRNAs essential for sperm development, such as CFAP61 and FSIP2 mRNAs, into phase-separated condensates, thereby regulating their translation through a mechanism of liquid-liquid phase separation.
Synonyms: CCDC46; MGC33887; MACOCO; SPGF44
Tractability: Antibody: its Gene Ontology location is reachable by antibodies, with medium confidence. PROTAC: ubiquitination databases record sites on it.
Gene: Protein-coding gene on chromosome 17 (65,635,537 to 66,192,251, reverse strand). Ensembl gene ENSG00000154240.
Subcellular location: Cytoplasm, cytoskeleton, microtubule organizing center, centrosome; Nucleus; Cytoplasm; Cytoplasm, Cytoplasmic ribonucleoprotein granule; Cytoplasm, cytoskeleton, flagellum axoneme; Cytoplasm, cytoskeleton, microtubule organizing center, centrosome, centriole
Subcellular location (Human Protein Atlas): Centrosome; Nucleoplasm; Cytosol; Midbody ring
Gene Ontology:
Molecular function: molecular condensate scaffold activity; protein binding
Cellular component: centrosome; cytoplasm; nucleus; centriole; cytoplasmic ribonucleoprotein granule; inhibitory synapse; plasma membrane; sperm head-tail coupling apparatus
Genetic constraint (gnomAD): Loss-of-function variants: 54 observed, 74.47 expected, observed/expected ratio (o/e) 0.73, 90% interval 0.58 to 0.91. The upper end of that interval is the gene's LOEUF score, 0.91, which puts it in group 3 of 6, group 1 being the genes least tolerant of losing a copy. Missense variants: 628 observed, 687.99 expected, observed/expected ratio (o/e) 0.91, 90% interval 0.85 to 0.98. Synonymous variants: 229 observed, 250.43 expected, observed/expected ratio (o/e) 0.91, 90% interval 0.82 to 1.02.
Homologues: Orthologues: chimpanzee CEP112 (99% identical), macaque CEP112 (97% identical), dog CEP112 (91% identical), rabbit CEP112 (89% identical), pig CEP112 (87% identical), mouse Cep112 (87% identical), rat Cep112 (86% identical), tropical clawed frog cep112 (59% identical), zebrafish cep112 (56% identical).
Diseases named in the same sentence as CEP112 in open-access papers:
CEP112 is named in the same sentence as 13 diseases in open-access papers, as found by Europe PMC text mining. Sharing a sentence is not in itself a finding about the gene and the disease. The quoted sentences say what the papers report.
Infertility (2 papers, 2022 to 2025). "Mutations in centrosomal proteins such as Cep112, Cep250, Cntrob, and Odf1 result in defects in head-tail attachment and can lead to headless sperm and non-obstructive azoospermia that contributes to infertility." (PMID 40294089, 2025).
acephalic spermatozoa syndrome (1 paper, 2021). "Moreover, mutations in centrosomal protein 112 (CEP112) can also lead to acephalic spermatozoa syndrome in humans." (PMID 34422805, 2021). "BRDT, DNAH6, CEP112, and HOOK1 have also been reported to be associated with acephalic spermatozoa syndrome." (PMID 34422805, 2021).
Alzheimer disease (1 paper, 2025). A progressive, neurodegenerative disease characterized by loss of function and death of nerve cells in several areas of the brain leading to loss of cognitive function such as memory and language. "Additionally, TPBG and CEP112 have been shown to be related to glioblastoma and Alzheimer’s disease." (PMID 41245832, 2025).
Azoospermia (1 paper, 2025). Absence of any measurable level of sperm,whereby spermatozoa cannot be observed even after centrifugation of the semen pellet. "These centrosome components are critical for maintaining the head-tail attachment, as exemplified by the fact that mutation of centrosomal genes Cep112, Cep250, Cntrob, and Odf1, lead to acephalic spermatozoa (headless sperm) and non-obstructive azoospermia." (PMID 40294089, 2025).
male infertility (1 paper, 2021). The inability of the male to effect fertilization of an ovum after a specified period of unprotected intercourse. "It is highly expressed in testes and is essential for maintaining sperm function: loss-of-function mutations in CEP112 have recently been associated with male infertility." (PMID 34515025, 2021).
metastasis (1 paper, 2023). The spread or migration of cancer cells from one part of the body (where they first appeared) to another. "CEP112 can be used as a DNA methylation biomarker associated with the risk of cancer liver metastasis in patients with early-stage CRC." (PMID 37965330, 2023).
cancer (2 papers, 2022 to 2023). A tumor composed of atypical neoplastic, often pleomorphic cells that invade other tissues. "One article from India suggested that the mutual interaction between Centrosomal Protein 112 (CEP112) and breast cancer type 1 susceptibility protein (Brca1) was significant in the mitotic regulation and maintenance of genomic stability." (PMID 36552760, 2022).
neurological disorders (1 paper, 2025). "The TPBG and CEP112 genes, which are implicated in neurological disorders, may offer insights into the onset of ALD." (PMID 41245832, 2025).
CEP112 also shares sentences with these, for which no sentence is quoted: glioma (2 papers); tumor (2); glioblastoma (1); infection (1); rheumatoid arthritis (1).